IGF1R (insulin like growth factor 1 receptor)
Diseases named in the same sentence as IGF1R in open-access papers (continued):
Sharing a sentence is not in itself a finding about the gene and the disease.
cancer (continued). "Both cancer and stromal cells produce IGF-2 and therefore IR-A, in addition to IGF-1R, mediates the mitogenic and antiapoptotic effects of IGF-2." (PMID 30453495, 2018). "The IGF system analysis of cancer thyrospheres is further complicated by the possibility of the generation of IR/IGF-1R hybrids by random assembly IR and IGF-1R hemidimers." (PMID 30513575, 2018). "Activated IGF1R induced the phosphorylation of STAT, which consequently enhanced ALDH1 expression, followed by reinforcement of the cancer stemness and radioresistance of non-small cell lung cancer (NSCLC) cells." (PMID 30013043, 2018). "Given recent evidence showing the role of autophagy in resistance to anti-cancer therapies, including PI3K/AKT therapies, and the involvement of IGF1R in autophagy, we investigated the role of IGF1R in GDC0032-induced autophagy in our OC cells." (PMID 30237504, 2018). "Under the influence of CAF-secreted IGF1 and SDF-1 (stromal-derived factor-1) a subpopulation of cancer cells that expressed the IGF1 receptor IGF1R and the SDF-1 receptor CXCR4 outgrew other cancer cell subpopulations." (PMID 29774124, 2018). "On the contrary, IGF-1R is overexpressed in small cell lung cancer (SCLC) and its inhibition affects cancer cell growth." (PMID 30111747, 2018). "Binding of insulin-like growth factor-I (IGF-1) to its receptor (IGF-1R) initiates downstream signals that activate PI3K/Akt/mTOR and MEK/Erk pathways, which stimulate cancer cell proliferation and induce drug resistance." (PMID 29843755, 2018). "Our previous studies suggested that α6β4, another integrin that is overexpressed in cancer cells, is critically involved in IGF1/IGF1R signaling through direct binding to IGF1." (PMID 28873464, 2017). "Insulin-like growth factor 1 receptor (IGF1R) is a transmembrane heterotetrameric protein that has been reported to promote transformation to malignancy and cancer cell proliferation and survival." (PMID 29156819, 2017). "Prognostic studies of insulin-like growth factor-1 receptor(IGF-1R) inhibitors in cancer therapy had promising results in infratests, which exhibited that IGF-1R signalling was crucial in cancer cells growth." (PMID 28427155, 2017). "Here, we found mutated genes at the level of the receptor itself in 7% of cases: focal amplification of IGF1R (n=3) and of IGF1 (n=2); frameshift indels in the recessive cancer genes, IGF2R (n=2) and IGFBP5 (n=1)." (PMID 28643781, 2017). "To date, it has been well established that miR-7 directly targets many oncogenic factors and is involved into multiple cancer-related signalling pathways, including EGFR, IRS-1/2, Raf1, Pak1, Ack1, PA28-gamma, IGF1R, PIK3CD and mTOR32–38." (PMID 28710406, 2017). "Dozens of eIF4E2 mRNA targets have strong ties to cancer such as a group of receptor tyrosine kinases including EGFR, platelet-derived growth factor receptor-alpha, insulin-like growth factor 1 receptor, and HER-2, which most cancers overexpress at least one." (PMID 29317983, 2017). "The autocrine IGF2, in turn, activated insulin-like growth factor 1 receptor (IGF1R), insulin receptor (INSR), followed by PI3K/AKT pathway and RAS/ERK pathway to promote cancer cell proliferation and survival." (PMID 28521298, 2017). "The protein levels of IGF1R in R‐WT and R‐TSM were essentially in the range of those in common cancer cell lines." (PMID 28112398, 2017). "Thus, it is possible that IGF1R expression could be derived from non-cancer cells." (PMID 28489591, 2017). "Ectopic insertion of miR-375 resulted in a significant reduction of IGF1R expression and its downstream signaling molecule AKT at both mRNA and protein levels in other cancer cell lines." (PMID 27129171, 2016). "IGF-1R is the primary mitogenic receptor of the IGF system that is overexpressed and has increased tyrosine kinase activity in several cancer types including PDAC." (PMID 27127884, 2016).
cancer (continued). "miR-16 has an important role in regulating apoptosis in different cancer types including lung, breast, liver, glioblastoma, and squamous cell carcinoma through targeting FEAT/METTL13, RPS6KB1, IGF1R, CCND1, BCL2, RECK, and/or SOX6." (PMID 27128908, 2016). "The release of miR-375 in exosomes, the down regulation of IGF1R, SNAIL1 and upregulation of E-cadherin suggest a likely effect of AE on the interaction between cancer cells and their environment." (PMID 27129171, 2016). "It opens new avenues of investigations of multiple inhibitory targets (ER-α, IGF-1R and EGFR) for wet lab experiments as well as provided valuable insights in the treatment of cancers such as BC." (PMID 27781158, 2016). "EGFR is overexpressed in many aggressive cancers, and previous study indicates that p85α can be activated by transmembrane tyrosine kinase receptors, such as EGFR, HER2 and IGF1-R." (PMID 26918608, 2016). "Similar results were shown in the MKR tumors, where approximately 73 % of the cancer cells were CD24+ following implantation of the CD24+ control cells, and only approximately 10 % were CD24+ in the CD24+ IGF1R-KD tumors." (PMID 27179633, 2016). "Herein, we tested the combination of metformin with CP treatment and we observed an additive anti-cancer effects when targeting NSCLC cell lines, which we think is partially mediated through IGF-1R down-regulation and signaling attenuation." (PMID 27488947, 2016). "Previous studies have found that IGF1R, as a target gene of miR-375 in LSCC, regulates the cell progression of cancers through AKT pathways." (PMID 28078305, 2016). "Among the predicted targets of miR-122, ADAM10, IGF1R, and CCNG1 play key roles in tumorigenesis and drug sensitivity in various cancers." (PMID 26514126, 2015). "Collectively, these findings indicate that blockade of the IGF1R with cix induces IGF1 to bind to integrin β3, which in turn induces Src signaling that increases cancer cell growth." (PMID 25699021, 2015). "New advances in the molecular basis of anti-IGF1R blocking antibodies reveal they are biased agonists and promote the binding of IGF1 to integrin β3 receptors in some cancer cells." (PMID 25699021, 2015). "Analysis of data from The Cancer Genome Atlas (TCGA) using the cBIO portal across most cancer types shows genomic alterations in IGF ligands (IGF1, 2), receptors (IGF1R, IGF2R), binding proteins (IGFBP1–6), and IRSs (IRS1, 2, 4); this representing 18 genes." (PMID 25964777, 2015). "In many cancers, these alternative RTKs including MET, IGF1R, FGFR and EphA2 become activated or amplified in order to maintain the signals for cell survival and/or proliferation in common downstream pathways, thus nullifying the inhibition of EGFR kinase." (PMID 25599599, 2015). "The insulin-like growth factor 1 receptor (IGF1R) and the insulin receptor (IR) are receptor tyrosine kinases that are expressed in cancer cells." (PMID 25699021, 2015). "Several studies have reported extensive cross-talk between IR (insulin receptor)/IGF1R (insulin-like growth factor-1 receptor) and EGFR/ErbB signaling pathways contributing to acquired drug resistance in various cancers." (PMID 25599599, 2015). "Our results demonstrated that the increasing concentration of curcumol decreased the level of IGF-1R, indicating that IGF-1R was involved in the anti-cancer mechanism of curcumol in LoVo cells." (PMID 26307972, 2015).
cancer (continued). "IGF1R is considered the main receptor responsible for the mitogenic effects of the IGF axis, therefore, it represents an attractive target for anti-cancer therapy." (PMID 25225571, 2014). "Activation of the insulin-like growth factor-1 receptor (IGF1R) is essential for survival of many oncogenic cells and its important role in cancer is well established." (PMID 25362932, 2014). "This review will follow the development of our understanding of IGF-1R signaling and relate it to the models considered when different IGF-1R-targeting strategies are designed, in particular with regards to cancer therapy." (PMID 24276851, 2014). "IGF-1R and INSR belong to the IGF signaling pathway, which plays central roles in cell growth, differentiation, survival, cell transformation and cancer metastasis." (PMID 24816813, 2014). "In both the primary cancers and the metastases, Claudin-4 was most frequently expressed, followed by GLUT-1, CAIX, EGFR and IGF1R." (PMID 25417118, 2014). "This drug compared with the other class of IGF1R blockers has the advantage to inhibit also the IGF2-induced IRA activation, which has been reported to favour growth in cancer." (PMID 25225571, 2014). "Akt activation promotes signaling in the IGF-1R/IRS-1 axis, which contributes to the dysregulation of NFκB and, ultimately, cancer cell growth." (PMID 25533015, 2014). "Third, this RTKs-targeting degradation strategy can be combined with antibodies or small molecule inhibitors against RTKs, especially when kinase-independent biologic functions of RTKs, such as IGF-1R and EGFR, also contribute to cancer malignancy." (PMID 24970814, 2014). "We now extended our study and investigated the impact of IGF1R and INSR level modulations on colony formation ability, an additional cancer-promoting feature." (PMID 24809298, 2014). "However, nearly twice as many 4N cells are Igf1r (or Pdgfra) positive versus Igf1r (or Pdgfra) negative, suggesting these Pax3:Foxo1a targets may have a functional role late in the cell cycle, such as the Igf1r-mediated radioresistance seen for other forms of cancer." (PMID 24453992, 2014). "Recent findings evidenced a synergistic interaction between MET and other RTKs, like EGFR, vascular endothelial growth factor receptor (VEGFR) and insulin-like growth factor-1 receptor (IGF-1R), promoting cancer invasiveness and resistance to chemotherapy." (PMID 28548075, 2014). "Previous studies have indicated that crosstalk between IGF1R and other tyrosine kinases such as HER2 and EGFR can drive cancer progression and drug resistance." (PMID 24655723, 2014). "The IR is not the only RTK associated with the IGF-1R; for example, a direct interaction between the IGF-1R and EGFR was identified in cancer cells, with EGFR depletion affecting IGF-1R ubiquitination, degradation, and signaling." (PMID 24276851, 2014). "The contradictions to the classical IGF-1R signaling concept as well as the design of anti-IGF-1R therapeutics treatment are considered in the light of this paradigm shift and we advocate recognition of IGF-1R as a valid target for cancer treatment." (PMID 24276851, 2014). "Paradoxically, a number of studies have demonstrated positive effects of IGF-1R and IGF-1 in conferring radiation resistance, mostly through prevention of apoptosis in some cancer cell types." (PMID 24205274, 2013). "The MDM2-mediated IGF-1R ubiquitination activates the ERK pathway and leads to the cancer resistance to PPP." (PMID 24182354, 2013). "Deregulation of the IGF signaling pathway frequently occurs in human cancer and involves the establishment of autocrine loops comprising IGF-1 or IGF-2 and/or IGF-1R over-expression." (PMID 23525758, 2013). "IRS1 has been shown to be involved in cancer progression and metastasis by mediating proliferative and anti-apoptotic functions of the INSR and IGF1R signaling." (PMID 23818951, 2013).
cancer (continued). "Tumors with IGF1R-positive and IGFBP3-negative expression (n = 32) were significantly frequently found to have Stage II and III cancer (χ2 test, p = 0.011) compared to the other groups (n = 90)." (PMID 23962053, 2013). "Its activation has been shown to compensate IGF-1R inhibition in malignant cells, thus validating the interest of co-targeting IGF-1R and IR in cancer." (PMID 23696913, 2013). "The available data from the first clinical trials with agents targeting the IGF-1R have been positive enough to launch several phase II and III trials in various human cancers." (PMID 23525758, 2013). "Anti-cancer strategies targeting the IGF signaling system involve two main approaches, namely neutralizing antibodies and small molecule inhibitors of the IGF-1R kinase activity." (PMID 23525758, 2013). "PPD and MβCD modulate lipid raft-dependent signaling pathways including IGF-1R, pAkt, PARP, Caspase-8 and Bid in two different cancer cells." (PMID 23889969, 2013). "In the sensitive lines HCT-8 and SW948, PPP treatment blocks IGF-1R phosphorylation and inhibits its downstream AKT and ERK pathway, and suppresses carcinoma cell growth and xenograft progression." (PMID 24182354, 2013). "The IGF-1 pathway, whose genes IGF1R, IGF-1 and IGFBP-3 are among the target genes of the differentially expressed miRNAs, plays a critical role in cancer development, including ES." (PMID 22429812, 2012). "PI3K/Akt signalling is one of the most critical cancer-promoting pathways through upregulation of growth factor receptors (EGFR, IGF1R, HER2, etc) or PTEN inactivation and recently considered a major determinant of trastuzumab resistance." (PMID 22454081, 2012). "Among the IGF family proteins, IGF-1, IGF-1R and IGF-2 are positively correlated to cancer formation." (PMID 23071652, 2012). "Apoptosis induction was preceded by marked inhibition of IGF-1R, cyclin D1, β-catenin, and Notch-1 expression in pancreatic cells, but only IGF-1R, cyclin D1, and β-catenin in the cancer stem-like cells." (PMID 22570653, 2012). "A biochemical link between cancer and T2DM exists, because signaling through insulin receptor and insulin like growth factor 1 receptor (IGF-1R) is increased in the hyperinsulinemic condition of diabetics." (PMID 22829853, 2012). "Numerous therapeutic agents and antibodies have been developed targeting IGF-1R, EGRR and VEGFR signaling pathways with intention to block cancer cell proliferation, angiogenesis or revert drug resistance." (PMID 23369397, 2012). "A second finding from this study is the increase in phosphorylated, activated IGF-1R and MET cell membrane growth factor receptors in CALU-3 cancer cells with acquired resistance to the four TKIs." (PMID 21750552, 2011). "In cancers, HIF-1 participates in the activation of autocrine signaling pathways involving TGF-a/EGFR and EGF-2/IGF-1R, which promote cell survival and proliferation." (PMID 21492463, 2011). "The receptor tyrosine kinase insulin like growth factor-1 receptor (IGF-1R) and its ligands, IGF-1 and IGF-2, are essential for cell growth and development but also in the progression of various types of cancer, including HCC." (PMID 21569410, 2011). "As the IGF axis is a central regulator of growth and survival, therapeutic strategies focusing on the blockage of IGF1R and IGF signalling are currently being investigated for several types of cancer in a large number of clinical trials." (PMID 20924377, 2010). "In contrast to the EMT/mesenchymal markers, many genes downstream of AKT and related cancer-relevant pathways (PI3-Kinase, PTEN, IGF1R, mTOR and S6 Kinase) are induced when PC-3 and PC-3M cells become invasive." (PMID 20454659, 2010). "A-982605 is selective at inhibiting IGF1R and effective as a single agent or in combination with clinically approved agents targeting EGFR in several cancer models in vivo." (PMID 19732452, 2009).
cancer (continued). "Growth receptor signaling via IGF1R and EGFR has been known to induce cell survival and proliferation in cancer cells via activation of the PI3Kinase and Akt pathway." (PMID 19323821, 2009). "IGF-II also participates in non-canonical processes such as maintenance of cancer stem-like states via the IGF-II/IGF-1R/Nanog axis." (PMID 41511360, 2026). "We investigated the role of IGF-1R in DNA double-strand break (DSB) repair by assessing chromatin recruitment of DNA repair proteins, repair pathway usage, and therapeutic sensitivity in cancer cell models with altered IGF-1R status." (PMID 42095258, 2026). "Furthermore, sustained IGF‐1R activation induces the epithelial‐mesenchymal transition (EMT), increasing cancer invasiveness and metastasis." (PMID 40387523, 2025). "The combinations include EGFR inhibitor, IGF1-R/IR inhibitor, Akt inhibitor, and mTOR inhibitor that can directly or indirectly target different components of the PI3K/Akt/mTOR pathway a crucial signaling cascade in several cancers." (PMID 41427337, 2025). "Furthermore, cancer cells often activate compensatory pathways, such as HER2 or RAS/MAPK signalling, in response to IGF1R inhibition, diminishing therapeutic efficiency." (PMID 39796756, 2025). "Further research on the exact functions of IGF1R and IR in PDAC, including their specific roles in cancer cell growth, differentiation, and migration, will contribute to a more comprehensive understanding of their roles in disease development and the development of related drugs." (PMID 39948335, 2025). "Furthermore, histological and immunohistochemical staining revealed a significant upregulation of IGF1R in HCC tissues, particularly in the membranes of cancer cells." (PMID 40530890, 2025). "Indeed, the expression of IGF1R, IGF2R, FGFR2-4, and de novo fatty acid biosynthetic enzymes (ACC1, FASN) correlates with ferroptosis resistance across 824 primary, adherent cancer cell lines." (PMID 40000627, 2025). "Additionally, metformin inhibits IGF‐1R autophosphorylation, reducing downstream PI3K/AKT/mTOR and MAPK pathway signaling, which limits cancer cell proliferation and survival." (PMID 40387523, 2025). "Transduction of these retroviral particles showed cancer gene therapy properties as, in fact, vLTR-IGF-IRAS retroviral particles reduced the IGF1R levels and inhibited the in vitro proliferation, migration, and invasion of highly metastatic carcinoma H-59 cells." (PMID 38892104, 2024). "The targeted inhibition of IGF-1R in cancer treatment yields more benefits than traditional non-selective treatments like chemotherapy and radiation therapy, which can harm normal cells." (PMID 38540176, 2024). "In addition, sh-IGF1R cSCCs showed a significant reduction in the expression of ITGAV and in the percentage of ITGAV+ cancer cells compared with sh-control ones, indicating a loss of plasticity following IGF1R abrogation." (PMID 39075581, 2024). "The generation of mesenchymal EpCAMneg cancer cells from epithelial plastic cancer cells was significantly reduced in sh-ITGAV-derived tumors, leading to a strong accumulation of EpCAMhigh cancer cells, similarly to that observed in the sh-IGF1R cSCCs." (PMID 39075581, 2024). "The role of the IGF1/IGF1R axis in directly modulating MDSCs activity in cancer, has not yet been deeply investigated." (PMID 38420122, 2024). "Combining multiple agents and fine-tuning selective inhibitors which spare IR while impairing the pro-cancer functional significance of IGF-1 might be accomplished by further examining the structural differences and binding peculiarities of IGF-1R and IR." (PMID 39273251, 2024). "Recent evidence in glioma confirms the anti-cancer properties of vLTR-IGF1RAS particles, which determined a significant decrease in IGF1R expression, reduced cell proliferation, increased apoptosis, and reduced anchorage-independent growth in 3D spheroid assays." (PMID 38892104, 2024).